VHL (von Hippel-Lindau tumor suppressor)
Diseases named in the same sentence as VHL in open-access papers (continued):
Sharing a sentence is not in itself a finding about the gene and the disease.
multiple endocrine neoplasia (5 papers, 2013 to 2023). Multiple endocrine neoplasia (MEN) is a group of rare inherited cancer syndromes characterized by the development of two or more endocrine gland tumors, sometimes with tumor development in other tissues or organs. "The mean age at presentation was 52 years; 55% were female patients, 11% were associated with MEN1 (multiple endocrine neoplasia 1) or VHL (Von Hippel–Lindau); mean tumor diameter was 3.3 cm (standard deviation, SD) (2.92)." (PMID 24403235, 2013). "Second, our study did not include tumor markers, such as CA19-9 and CEA, and clinical syndromes (e.g., multiple endocrine neoplasia syndromes) or genetic syndromes (e.g., mutations in MEN1, VHL, or other relevant genes)." (PMID 38087239, 2023). "The clinical syndromes (e.g., multiple endocrine neoplasia [MEN] syndromes) or genetic syndromes (e.g., mutations in MEN1, VHL, or other relevant genes) could occur in PNENs." (PMID 38087239, 2023). "Examples of PPGLA mutations include the RET gene in multiple endocrine neoplasia (MEN) syndromes, the VHL gene in von Hippel–Lindau disease, the NF1 gene in Neurofibromatosis type 1, the MAX gene, or the genes of the succinate dehydrogenase complex (SDHB, SDHD, SDHA, SDHC, SDHAF2)." (PMID 36010170, 2022).
pancreatic ductal adenocarcinoma (5 papers, 2021 to 2025). An infiltrating adenocarcinoma that arises from the epithelial cells of the pancreas. "UBE2S was demonstrated to promote the epithelial-mesenchymal transition (EMT) through the VHL/HIF-1α/STAT3 signaling pathway in pancreatic ductal adenocarcinoma." (PMID 34535173, 2021). "Intriguingly, we found that high expression of VHL is positively correlated with higher recurrence-free survival not only in TNBC, but also in other wild-type VHL harboring cancers, like pancreatic ductal adenocarcinoma and rectum adenocarcinoma, which is consistent with previous studies." (PMID 36813923, 2023). "We previously demonstrated that our dTAG molecules known as dTAGV-1 and dTAG-13, which recruit von Hippel-Lindau (VHL) or cereblon (CRBN), respectively, are selective and degrade KRASG12V in several cellular models, including pancreatic ductal adenocarcinoma cell lines." (PMID 39718828, 2024).
renal fibrosis (5 papers, 2017 to 2023). A final common manifestation of a wide variety of chronic kidney diseases characterized by glomerulosclerosis and tubulointerstitial fibrosis. "We illustrated that SETD2 deficiency promotes renal fibrosis in VHL‐deficient mice by the activation of the TGF‐β/Smad signalling pathway." (PMID 37933774, 2023). "Together, these results indicated that SETD2 deficiency resulted in severe renal fibrosis in VHL‐deficient mice." (PMID 37933774, 2023). "To explore the mechanisms by which SETD2 deficiency promotes renal fibrosis in VHL‐deficient renal tubular epithelial cells, we performed RNA sequencing using PTECs freshly isolated from 10‐week‐old VHL−KO and VHL−KO; Setd2−KO mice." (PMID 37933774, 2023). "Accordingly, stabilization of both HIF1 and HIF2 in a 5/6 renal ablation model of VHL–/– mice was also associated with exacerbated renal fibrosis, and treatment with YC-1, an anti-HIF-1 agent, inhibited the progression of renal fibrosis in UUO model mice." (PMID 28900259, 2017). "SETD2 deficiency leads to severe renal fibrosis in VHL‐deficient mice." (PMID 37933774, 2023). "SETD2 and Von Hippel–Lindau (VHL) double‐knockout mice were used to further investigate the role of SETD2 in renal fibrosis." (PMID 37933774, 2023). "The mRNA expression of VHL in the kidneys with renal fibrosis was also reduced compared to that in normal kidneys." (PMID 37933774, 2023). "Meanwhile, the mRNA expression of SETD2 is positively correlated with VHL in both kidneys with renal fibrosis and normal kidneys." (PMID 37933774, 2023). "In summary, we established a mouse model of renal fibrosis driven by deficiency of SETD2 and VHL." (PMID 37933774, 2023). "Refer to this strategy, we designed and constructed a novel Smad3-targeting, VHL-recruting PROTAC and confirmed its effects on anti-renal fibrosis and renal function-improving." (PMID 36536448, 2022). "Here, we established a mouse model of renal fibrosis driven by the inactivation of SETD2 and VHL." (PMID 37933774, 2023). "Deletion of SETD2 leads to reduced Smad7 expression, which results in activation of the TGF‐β/Smad signalling pathway and ultimately renal fibrosis in the absence of VHL." (PMID 37933774, 2023). "In mouse UUO model, global or conditional knockout of HIF in myeloid cells show more severe inflammation, while HIF activation by myeloid-specific VHL-knockout only suppresses inflammation but without obvious effect on renal fibrosis." (PMID 28468297, 2017). "As VHL–/– mice likely expressed a high level of HIF when CKD was generated, a high HIF level at the initiation of renal fibrosis might induce the profibrotic pathway cascade." (PMID 28900259, 2017). "SETD2 deficiency resulted in severe renal fibrosis in the absence of VHL, and based on these results, we found that SETD2 deletion can lead to reduced expression of Smad7 by H3K36me3, which activates the TGF‐β/Smad signalling pathway and leads to renal fibrosis." (PMID 37933774, 2023).
tumor predisposition syndrome (5 papers, 2017 to 2026). "Von Hippel-Lindau (VHL) disease is a hereditary tumor predisposition syndrome caused by pathogenic germline variants in the VHL gene." (PMID 42313274, 2026). "Von Hippel-Lindau (VHL) disease describes a hereditary tumor predisposition syndrome, caused by germline mutations in the VHL tumor suppressor gene, resulting in the functional loss of the VHL protein (pVHL)." (PMID 40753869, 2025). "Additionally, these results provide a framework moving forward for future investigation into genotype-phenotype correlations for VHL and other tumor predisposition syndromes." (PMID 28388566, 2017).
adrenal pheochromocytoma (4 papers, 2010 to 2025). "The VHL(NM_000551.4):c.576delA (p.Asn193MetfsTer9) variant was identified in young male patient (15 years old) presenting with hormonally active adrenal pheochromocytoma." (PMID 34439371, 2021). "Genetic disorders involving mutations within the succinate dehydrogenase B and D units (SDHB, SDHD) and the von Hippel-Lindau (VHL) gene places an increased risk in the development of extra-adrenal paragangliomas and adrenal pheochromocytomas, respectively." (PMID 21188160, 2010).
chondrosarcoma (4 papers, 2014 to 2022). A malignant cartilaginous matrix-producing mesenchymal neoplasm arising from the bone and soft tissue. "Loss of function of the wild type VHL allele in the tumor and loss of pVHL expression suggest that the chondrosarcoma is a canonical VHL manifestation in this patient." (PMID 31673890, 2020). "To conclude, we report a clear cell chondrosarcoma in a VHL patient that exhibited loss of pVHL expression due to loss of expression of the VHL gene." (PMID 31673890, 2020). "Loss of expression of the VHL protein (pVHL) suggests that clear cell chondrosarcoma may be part of the VHL tumor spectrum." (PMID 31673890, 2020). "We discuss the relevance of this observation with regard to the pathogenesis of clear cell chondrosarcoma in the context of VHL." (PMID 31673890, 2020). "Chondrosarcoma has been described before in a VHL patient and VHL protein expression has been correlated to tumor grade in a series of sporadic chondrosarcomas." (PMID 31673890, 2020). "Levels of both VHL mRNA and protein were found to be reduced in a significant proportion of chondrosarcomas compared with adjacent normal tissue." (PMID 31673890, 2020). "By the downregulation of Von Hippel-Lindau (VHL), miR-211 may function as an oncogenic in chondrosarcoma to modulate cell proliferation." (PMID 35912006, 2022). "In this report, we show that clear cell chondrosarcoma may be a rare but canonical VHL manifestation through a cell-autonomous mechanism involving somatic loss-of-heterozygosity of the VHL tumor suppressor gene." (PMID 31673890, 2020). "Our data support the notion that clear cell chondrosarcoma could be a rare but specific manifestation of VHL." (PMID 31673890, 2020). "Previously, a mildly differentiated chondrosarcoma has been reported in a VHL patient." (PMID 31673890, 2020). "We report a case of clear cell chondrosarcoma in a VHL patient." (PMID 31673890, 2020). "However, none of the known diseases caused by pathogenic variants in VHL are characterized by enchondromas or chondrosarcomas." (PMID 36480544, 2022).
hemangiosarcoma (4 papers, 2009 to 2017). "Here, we first tested the hypothesis that known genes that regulate VEGF, including VHL and members of the Ras family were targets of mutation in canine hemangiosarcoma." (PMID 21062482, 2010). "We first investigated mutations of VHL and Ras family genes that might drive hemangiosarcoma by sequencing tumor DNA and mRNA (cDNA)." (PMID 21062482, 2010). "Mutations in these genes appear to be similarly infrequent in canine hemangiosarcoma, as each of the tumor samples, as well as the splenic hematoma samples we evaluated in this study had wild-type sequence for VHL and for the three Ras family genes." (PMID 21062482, 2010). "We sequenced the complete coding domains for VHL, N-Ras, K-Ras, and H-Ras from 10 canine hemangiosarcoma cell lines and from four lines derived from splenic hematomas." (PMID 21062482, 2010). "Therefore, we conclude that the frequency of VHL or Ras mutations in sporadic canine hemangiosarcoma is unlikely to exceed 30%." (PMID 21062482, 2010). "In the case of canine hemangiosarcoma, PTEN mutations did not fully explain the increased levels of VEGF or other growth factors, prompting additional assessment of potential roles for mutations that inactivate VHL or that activate Ras, as both can lead to elevated VEGF production." (PMID 21062482, 2010).
Kidney Cyst (4 papers, 2017 to 2024). Abnormal fluid filled sac within the kidney, either acquired or congenital. "Due to the multifactorial nature of VHL, most of these patients would have other tumors, mostly benign, present in their bodies and likely have a greater number of kidney cysts than would be present in normal controls." (PMID 39062684, 2024).
liver cancer (4 papers, 2019 to 2025). An epithelial or non-epithelial malignant neoplasm that arises from the liver. "According to the COSMIC data, VHL displayed mutation rates of 39% and 33% in liver cancer and paratesticular tissues, respectively." (PMID 31729414, 2019). "We further validated the loss of function of VHL in HepG2, a human liver cancer cell line." (PMID 38853928, 2025).
lymph node metastasis (4 papers, 2021 to 2025). "This is consistent with our results regarding the association between the VHL expression level and lymph node metastasis." (PMID 40005423, 2025). "Only in combined analysis, patients with ≥ 2 variant alleles of all 4 polymorphisms in VHL and HIF1A genes (VHL rs779805, HIF1A rs11549465, HIF1A rs11549467, HIF1A rs2057482) in their study were significantly associated with localized clinical stage and less frequency of lymph node metastasis." (PMID 38115281, 2023).
medullary thyroid cancer (4 papers, 2006 to 2022). "VHL mutations have not been identified in the thyroid except in MEN 2 associated medullary thyroid carcinoma although LOH in the VHL gene has been identified in follicular carcinomas of the thyroid." (PMID 17067398, 2006). "We studied 6 medullary thyroid carcinomas and 1 C-cell hyperplasia specimen from 7 patients with MEN 2A and known RET germline mutations for allelic imbalance at the RET locus and for somatic genetic alterations at the VHL gene locus at 3p25/26 including LOH and mutations." (PMID 16707008, 2006).
tumor syndrome (4 papers, 2012 to 2021). "Von Hippel–Lindau (VHL) disease is a neoplastic syndrome caused by a mutation of the VHL tumor suppressor gene." (PMID 35008334, 2021). "Von Hippel-Lindau (VHL) disease (MIM #193300) is a rare hereditary tumor syndrome that results from a germline mutation in the VHL gene." (PMID 23384121, 2013).
acute lymphoblastic leukemia (3 papers, 2022 to 2023). Leukemia with an acute onset, characterized by the presence of lymphoblasts in the bone marrow and the peripheral blood. "Nevertheless, the protein level of VHL E3 ligase did not correlate with DT2216 cell death induction, as already reported in T-cell acute lymphoblastic leukemia cell lines." (PMID 37534243, 2023).
Alzheimer disease (3 papers, 2015 to 2024). A progressive, neurodegenerative disease characterized by loss of function and death of nerve cells in several areas of the brain leading to loss of cognitive function such as memory and language.
Autoimmunity (3 papers, 2023 to 2024). The occurrence of an immune reaction against the organism's own cells or tissues. "The VHL/HIF axis does, in fact, impact the transcription of numerous genes implicated in various mechanisms, including oncogenesis and autoimmunity." (PMID 36611440, 2023). "Although a similar interplay between neoplastic and autoimmune processes can be hypothesized in this case report, a clear link between clear cell NENs and autoimmunity against a VHL background cannot easily be substantiated, as such cases are quite rare." (PMID 38619811, 2024).
brain tumor (3 papers, 2010 to 2024). "Given the proximity of LINC011322 and VHL on chromosome 3, as well as the role of LINC011322 in neurogenesis, it is possible that LINC011322 plays a significant role in ccRCC and brain tumors, which are associated with VHL syndrome, through its interaction with VHL." (PMID 39886373, 2024). "In RCC the CA IX induction is associated with VHL-mutation and not with hypoxia as in brain tumours." (PMID 20398423, 2010). "Correspondingly, IHC analysis of the removed mouse brain tumor sections confirmed the high expression of FBXO22, HIF-1α and VEGFA and low expression of VHL in the U87-FBXO22 group compared with the U87-Vector group." (PMID 38519492, 2024).
breast tumor (3 papers, 2021 to 2024). "In summary, these findings indicate that VHL suppresses breast tumor growth and lung metastasis by inhibiting UBE3B." (PMID 38914543, 2024). "Collectively, these results indicate that VHL inhibits UBE3B-mediated breast tumor growth and lung metastasis in mice." (PMID 38914543, 2024). "Our next objective was to investigate VHL’s role in UBE3B-mediated breast tumor growth and metastasis in vivo." (PMID 38914543, 2024). "As anticipated, Flag-VHL led to decreased spontaneous breast tumor growth, a phenomenon effectively counteracted by Myc-UBE3B." (PMID 38914543, 2024). "The K286/427R mutation of UBE3B dramatically abolishes the inhibitory effect of VHL on breast tumor growth and lung metastasis." (PMID 38914543, 2024). "Taken together, these data convincingly demonstrate that VHL inhibits breast tumor growth and metastasis by promoting UBE3B degradation." (PMID 38914543, 2024). "In the present study, we identified UBE3B as a bona fide VHL substrate in breast tumors." (PMID 38914543, 2024). "VHL-mediated UBE3B degradation suppresses breast tumor growth and metastasis." (PMID 38914543, 2024). "CP5V specifically degrades CDC20 by bridging CDC20 to the VHL/VBC complex for ubiquitination-mediated degradation, suppressing breast tumor progression." (PMID 35954396, 2022). "Importantly, the protein levels of VHL and UBE3B have a negative correlation in breast tumors." (PMID 38914543, 2024).
chromophobe carcinoma (3 papers, 2012 to 2023). "VHL mutations were reported in 59.3% of clear cell, 5.2% of papillary, 3.1% of chromophobe carcinomas." (PMID 37891555, 2023). "VHL and SDHB mutations were investigated using genomic DNA extracted from paraffin-embedded tumor sections (both from the seminal vesicle tumor and from the chromophobe renal cell carcinoma)." (PMID 22344361, 2012).
chronic kidney disease (3 papers, 2022 to 2025). Impairment of the renal function secondary to chronic kidney damage persisting for three or more months. "Dysregulation of the VHL/HIF pathway is implicated in various diseases, including several cancers and chronic kidney disease, where an abnormal oxygen response plays a pivotal role." (PMID 39858553, 2024). "In addition to cancer, modulating the VHL/HIF pathway holds potential in treating conditions characterized by chronic hypoxia, such as pulmonary hypertension and chronic kidney disease." (PMID 39858553, 2024).
ciliopathy (3 papers, 2013 to 2021). A genetic disorder of the cellular cilia or the cilia anchoring structures, the basal bodies, or of ciliary function. "Von Hippel-Lindau (VHL) disease is an atypical ciliopathy and inherited tumor syndrome, caused by a mutation in the VHL tumor suppressor gene encoding the VHL protein (pVHL)." (PMID 23384121, 2013). "Loss of VHL results in a corresponding loss of primary cilia categorizing VHL as a ciliopathy—a growing collection of diseases characterized by absent/aberrant primary cilia." (PMID 34002003, 2021).
colitis (3 papers, 2018 to 2023). Inflammation of the colon. "Moreover, conditional knockout of HIF1α exacerbated inflammation in TNBS-induced colitis in mice, while increased HIF1α activation via knock-out of the von Hippel–Lindau (VHL) gene was protective." (PMID 38163085, 2023). "Because VHL loss results in constitutive activation of HIF-1α/2α, we wanted to determine whether DSS-induced colitis features that were observed in hMRP8 Vhl KO mice would be reversed in myeloid-specific hMRP8 Hif-1a KO mice." (PMID 29967068, 2018).
cystadenoma (3 papers, 2012 to 2019). A benign or borderline cystic epithelial neoplasm arising from the glandular epithelium. "One mouse developed an epididymal clear cell papillary cystadenoma that appeared histologically identical to the cystadenomas that arise at high frequency in patients with an inherited VHL mutation." (PMID 23606570, 2013).
diabetes (3 papers, 2013 to 2026). "Here, the authors design a small molecule that stabilizes HIF1α by blocking its interaction with VHL and show that it promotes wound healing in mouse models of diabetes." (PMID 34099651, 2021). "This suggests that strategies to improve the stability of HIF-1α, such as by blocking the interaction between VHL and HIF-1α, could be a promising strategy for the treatment of diabetes wound complications." (PMID 34099651, 2021).
Ewing sarcoma (3 papers, 2020 to 2023). A small round cell tumor that lacks morphologic, immunohistochemical, and electron microscopic evidence of neuroectodermal differentiation. "The presence of a VHL gene mutation in a patient with ALL and Ewing sarcoma is unusual and might indicate genetic instability or the driver mutation is not in included our targeted 84 genes panel." (PMID 38021917, 2023). "Employing dTAGV-1 to study EWS/FLI, we demonstrate that VHL-mediated degradation of EWS/FLI rapidly alters downstream target protein expression and leads to pronounced growth defects in Ewing sarcoma cells, providing a powerful model system to investigate immediate consequences of EWS/FLI loss." (PMID 32948771, 2020).
Familial adenomatous polyposis (3 papers, 2011 to 2024). Familial adenomatous polyposis (FAP) is characterized by the development of hundreds to thousands of adenomas in the rectum and colon during the second decade of life. "As expected, MUTYH associated with recessive familial adenomatous polyposis, the only two homozygotes of which also carry biallelic MUTYH variants, had the highest allele frequency, followed by VHL, BRCA1, BRCA2, and PALB2." (PMID 39301547, 2024).